RNU6-1075P (RNA, U6 small nuclear 1075, pseudogene)
Gene: Small nuclear RNA gene on chromosome 10 (16,207,821 to 16,207,927, reverse strand). Ensembl gene ENSG00000201260.
Homologues: Orthologues: chimpanzee U6 (97% identical), mouse Gm22458 (90% identical), dog U6 (74% identical), pig U6 (69% identical). Paralogues in human: RNU6-29P (93% identical), RNU6-41P (93% identical), RNU6-1060P (92% identical), RNU6-1124P (92% identical), RNU6-116P (92% identical), RNU6-12P (92% identical), RNU6-13P (92% identical), RNU6-187P (92% identical), RNU6-25P (92% identical), RNU6-32P (92% identical), RNU6-393P (92% identical), RNU6-44P (92% identical), and 1290 more.